HIF1A (hypoxia inducible factor 1 subunit alpha)
Diseases named in the same sentence as HIF1A in open-access papers (continued):
Sharing a sentence is not in itself a finding about the gene and the disease.
hepatocellular carcinoma (continued). "In conclusion, in the present study we report that miR-20b is associated with poor overall survival of HCC patients, suggesting its potential prognostic values in this disease type, and identified HIF-1α and VEGF as direct targets of miR20b in hepatocellular carcinoma cells." (PMID 26612965, 2015). "We compared these observations with the expression of HIF1α on mRNA and protein level in hepatocellular carcinoma cell (HCC) tissues, which is known to remain highly expressed in hypoxic conditions found in cancerous tissue." (PMID 26029826, 2015). "MiR-199a inhibits cell proliferation in vitro and in vivo partly through down-regulation of HIF-1α in human hepatocellular carcinoma." (PMID 26065676, 2015). "Direct evidence has also revealed that activation of the PI3K/Akt/HIF-1α pathway plays a critical role in mediating hypoxia-induced drug resistance resulting in an unfavorable treatment outcome of hepatocellular carcinoma." (PMID 24765145, 2014). "A recent study has shown that silencing of HIF-1α gene using specific siRNA can significantly inhibit the proliferation of hypoxic CBRH-7919 rat hepatoma cells by inactivation of the PI3K/AKT signaling pathway." (PMID 25101278, 2014). "Mitochondrial dysfunction repressed the protein synthesis of HIF-1α as well as reduced its trans-activation activity through AMPK signalling in human hepatoma HepG2 cells." (PMID 25491408, 2014). "The authors later concluded that the antiangiogenic and anticancer effects of chaetocin against hepatoma were via deregulation of HIF-1α premessenger RNA splicing." (PMID 24775564, 2014). "Knockdown of miR-210 increased protein expression of miR-210 targeted genes, but decreased HIF-1α protein in hepatoma xenograft." (PMID 23618526, 2013). "Protein expression of HIF-1α and miR-210 targeted genes in human hepatoma xenograft was assessed by Western blot." (PMID 23618526, 2013). "HCV glycoproteins perturb tight and adherens junction protein expression, and increase hepatoma migration and expression of epithelial to mesenchymal transition markers Snail and Twist via stabilizing hypoxia inducible factor-1α (HIF-1α)." (PMID 22178269, 2012). "In human hepatoma cells, IL-1β also stimulates DNA binding and the protein accumulation of HIF-1α, indicating the close relationship between IL-1β and HIF-1α activity." (PMID 23166763, 2012). "Studies examining hypoxia dependent transcription of BMP4 in hepatocellular carcinoma cells (HCC) showed that HIF1α dependent regulation of BMP4 expression is indirect in these cells." (PMID 20585586, 2010). "The present study shows that the 2ME2-analog ENMD-1198 interferes with growth factor-induced signaling in hepatocellular carcinoma and effectively inhibits HIF-1α and STAT3 activation." (PMID 18651980, 2008). "Moreover, FAT10 limits the efficacy of anti-VEGF therapy for hepatocellular carcinoma by simultaneously stabilising multiple proteins, including HIF1α, β-catenin, STAT3, and TAB3 proteins." (PMID 40374601, 2025). "Moreover, studies have suggested that CXCL6 can be regulated by specific cell signaling pathways, such as the HIF-1α pathway in hepatocellular carcinoma and the IL4 pathway through the JAK-STAT mechanism in atopic dermatitis." (PMID 40070583, 2025). "Moreover, it has reported that USP14 and USP8 contribute to HIF-1α stabilization in ciliogenesis and hepatocellular carcinoma, respectively." (PMID 39757165, 2025). "This suggests that the combination of HIF-1α inhibition and ketogenic dietary intervention could serve as a broadly applicable therapeutic approach for hepatocellular carcinoma." (PMID 41465202, 2025). "However, in another study, it was found that knockdown of HDAC6 significantly upregulated the expression of HIF-1α and VEGFA in vivo and in vitro and promoted HIF-1α-mediated hepatocellular carcinoma (HCC) angiogenesis." (PMID 40260239, 2025).
hepatocellular carcinoma (continued). "Overexpression of HIF‐1 α in glioblastoma cells, hepatocellular carcinoma, and ovarian cancer may be insensitive to radiation or resistant to chemotherapy." (PMID 41427004, 2025). "For example, FABP4 enhances mitochondrial β-oxidation to reduce cisplatin-induced apoptosis in ovarian cancer, while FABP5 promotes chemoresistance in hepatocellular carcinoma through the HIF-1α pathway, and FABP6 enhances CRC resistance to oxaliplatin through KLF5-dependent transcription." (PMID 40717587, 2025). "It has been shown that IL-1β-induced solute carrier family 7 member 11 (SLC7A11) overexpression upregulates PD-L1 and colony-stimulating factor 1 (CSF1) through the α-ketoglutarate/HIF1α axis, promoting MDSCs recruitment and infiltration in the hepatocellular carcinoma tumor niche." (PMID 38609997, 2024). "Interestingly, high levels of these exosomes were found in hepatocellular carcinoma patients, and a low survival rate was associated with low VHL presence and high HIF-1α." (PMID 39697630, 2024). "Silencing PLAGL2 leads to a downregulation of HIF-1α expression in hepatocellular carcinoma." (PMID 39102510, 2024). "Likewise, Metformin can attenuate hepatoma cell proliferation by decreasing glycolytic flux via the HIF-1α/PFKFB3/PFK1 pathway and overcome MR-induced resistance of skin carcinoma to photodynamic therapy." (PMID 39588377, 2024). "For instance, adipocyte-derived exosomes containing miR-32a and miR-32b could activate the von Hippel-Lindau-HIF-1α (VHL-HIF-1α) pathway in hepatocellular cancer cells, leading to increased resistance to 5-FluoroUracile." (PMID 39697630, 2024). "Second, HIF-1α-induced EMT could create advantages for hepatoma cells to recruit IDO-overexpressing TAMs to repress T-cell response, and thereby facilitating immune escape via CCL20-dependent manner." (PMID 36845131, 2023). "Given that the metabolite SA is structurally similar to α-KG, an important regulator of the PHD2/HIF-1α axis, we assumed that accumulated SA may be responsible for activating the HIF-1α signaling pathway in GSTZ1-deficient hepatoma cells." (PMID 37906252, 2023). "Indeed, hypoxia accelerated Sphk activity via HIF-1A to generate S1P in the hepatocellular carcinoma cell line." (PMID 36719377, 2023). "Met could transcriptionally down-regulated the expression of MDR1 by modulating AMPK/mTOR pathway and inhibiting HIF-1α expression, leading to reverse multidrug resistance in hepatocellular carcinoma." (PMID 37828612, 2023). "Luteolin can regulate the mRNA expression of pro-proliferative genes, pro-apoptotic genes, and angiogenic molecules Uba2, VEGF, Fra-1, HIF-1α, and Rac1 in hepatocellular carcinoma HepG2 cells, thereby inhibiting the proliferative activity and angiogenesis of hepatocellular carcinoma cells." (PMID 37151401, 2023). "Our study clarified that curcumin could downregulate the expressions of HIF-1α/STAT3/VEGF signal transduction pathway in hepatocellular carcinoma, thus suppressing the proliferation and growth of the cancer cells." (PMID 37333486, 2023). "In hepatoma cells and rat livers, the up-regulation of InR expression may be attributed to the stabilization of HIF-1α, as the hydroxylation and subsequent degradation of HIF-1α are tightly regulated by prolyl-4-hydroxylases that rely on iron and oxygen." (PMID 37887373, 2023). "However, the exact role of regulation of HIF-1α/PFKFB3 in the pro-invasion effect induced by sorafenib in hepatocellular carcinoma needs further investigation." (PMID 37476196, 2023). "For example, the ARDB2 signaling could facilitate the progression and sorafenib resistance of hepatocellular carcinoma via inhibited autophagic degradation of HIF1α." (PMID 37377953, 2023).
hepatocellular carcinoma (continued). "Additionally, HIF-1α has been shown to inhibit the formation of both radiotherapy-induced DSBs and SSBs, followed by increased radioresistance in hepatocellular carcinoma." (PMID 36551540, 2022). "Studies have shown that USP29 is related to HIF-1α in hepatoma cells." (PMID 35875077, 2022). "For example, METTL3 synergizes with hepatitis B X-interacting protein (HBXIP) to regulate the abundance of m6A modification of hypoxia-inducible factor-1 alpha (HIF-1α), resulting in metabolic reprogramming and malignant progression of hepatocellular carcinoma cells." (PMID 36476503, 2022). "HIF-1a is a major transcription factor involved in the hypoxic response of hepatoma cells." (PMID 33537099, 2021). "Moreover, AMPK, PI3K/Akt pathway, HIF-1α, and c-Myc have emerged as aerobic glycolysis related proteins in hepatocellular carcinoma." (PMID 34638959, 2021). "It is reported that in hepatoma cells HIF-1α could suppress FAO by repressing the expression of acyl-CoA dehydrogenases (ACAD)." (PMID 34888248, 2021). "Similarly, curcumol downregulates HIF-1α and PD-L1 expression under hypoxia in hepatocellular carcinoma cells." (PMID 34575983, 2021). "Our results suggest that MOF regulates hypoxia tolerance and drug resistance in hepatocellular carcinoma cells by modulating both HIF-1α mRNA expression and N-terminal acetylation of HIF-1α, providing molecular insight into MOF-dependent oncogenic function of hepatocellular carcinoma cells." (PMID 34540836, 2021). "Our studies suggested that lncRNA-SNHG6 could promote the progression of hepatocellular carcinoma by targeting miR-6509-5p, and identified the cell cycle related protein, HIF1A, as the protein effector of the SNHG6/miR-6509-5p axis." (PMID 33663502, 2021). "HIF-1α is a key factor promoting the development of hepatocellular carcinoma (HCC)." (PMID 35095479, 2021). "In hepatocellular carcinoma, HIF-1α and TGF-β form a feedforward loop to induce EMT." (PMID 34284780, 2021). "This indicates that DEX attenuates HIF1α activity in a GR-dependent manner, since these effects are not present in a GR deficient human hepatoma Hep3B cell line and are restored upon transient expression of GR." (PMID 34149725, 2021). "In addition, YAP can bind to hypoxia-inducible factor 1α (HIF-1α) and maintain its protein stability, thus promoting hepatocellular carcinoma cell glycolysis under hypoxic stress." (PMID 33980319, 2021). "A previous study showed that the HIF1-α inhibitor, LW1564, inhibited mitochondrial respiration by reducing OCR and electron transport chain complex I, which decreased ATP production and promoted the degradation of HIF-1α, thus inhibiting the growth of hepatocellular carcinoma cells." (PMID 34451892, 2021). "In addition, the HIF1α/lncRNA Retinoic Acid Early Transcript 1K (RAET1K)/miR-100-5p axis modulates hypoxia-induced glycolysis in hepatocellular carcinoma (HCC) cells and affects HCC progression." (PMID 33652661, 2021). "We concluded that SNHG6/miR-6509-5p/HIF1A axis functioned in the progression of hepatocellular carcinoma, and could be the promising therapeutic targets during the development of hepatocellular carcinoma drugs." (PMID 33663502, 2021). "Interestingly, hypoxia increases RORα transcription in a hepatoma cell line by binding to a hypoxia response element in the RORα promoter, indicating the potential for reciprocal regulation of RORα and HIF-1α." (PMID 34756888, 2021). "In the process to evaluate the effect of hypoxia on cisplatin resistance in hepatocellular carcinoma cells, we notice an interesting difference in HIF-1α protein expression patterns: 5% O2 transiently increases HIF-1α protein levels in HepG2 cells but constitutively increases in HepG2/DDP cells." (PMID 33290263, 2020). "In addition, depletion or inhibition of CDK5 with roscovitine in hepatocellular carcinoma cell lines decreased expression of HIF-1α levels, and decreased expression levels of HIF-1α targets VEGFA, EphrinA1 in vivo and in vitro." (PMID 31910742, 2020).
hepatocellular carcinoma (continued). "Interestingly, the RNAi-mediated suppression of HIF-1α expression in the liver inhibited metastatic tumor growth in the hepatoma cell line (SMMC-7721) and tumor-bearing mouse liver." (PMID 32722054, 2020). "To investigate whether CK affected glycolysis in hypoxic hepatoma cells by modulating the ubiquitination of HIF-1α, we treated hypoxic hepatoma cell lines Bel-7404 and Huh7 with different concentrations of CK (20, 40, and 60 μM)." (PMID 33363466, 2020). "In a single study, miR-23a and miR-23b, encapsulated into exosomes derived from mature adipocytes, were able to promote the proliferation of BEL-7402 hepatocellular cancer cells, upregulating the expression of HIF-1α, Glucose Transporter 1(GLUT-1) and VEGF via von Hippel–Lindau (VHL) inhibition." (PMID 32235370, 2020). "BIX01294, a G9a-specific inhibitor, decreased expression levels of HIF1α, VEGFA, proline hydroxylase 2 (PHD2), hydroxylated HIF1α and von Hippel-Lindau protein (pVHL), as well as shortened the half-life of HIF1α in HepG2 human hepatocellular carcinoma cells under hypoxic conditions." (PMID 32070413, 2020). "Likewise, in hepatospheres obtained from hepatocellular carcinoma cell lines by incubation in a defined medium, a marked increase in ABCB1A and HIF‐1α was observed and was associated with drug resistance, concordant with our results." (PMID 30959553, 2019). "Similarly, Sorafenib treatment of hepatocellular cancer cell inhibits HIF-1α but triggers HIF-2α expression and resistance to the treatment." (PMID 31640284, 2019). "Nrf-2 is also required for the arsenite-mediated upregulation of HIF-1α in HepG2 hepatoma cells." (PMID 31527445, 2019). "Additionally, GSK360A treatment resulted in the accumulation of both HIF1α and HIF2α in a Hep3B human hepatoma cell line." (PMID 31375751, 2019). "And the overexpression of HIF-1α enhanced EMT of hepatoma cells." (PMID 31572568, 2019). "KN-62 has been shown to effectively suppress the expression of HIF-1α in hepatoma cells." (PMID 28289331, 2017). "However, little is known about the ability of this peptide to regulate HIF-1α in hepatic carcinoma cells." (PMID 28886081, 2017). "ID1 can stabilize HIF-1α protein in hepatocellular carcinoma cells." (PMID 27127787, 2016). "Indeed, high HIF1α levels were previously demonstrated to be responsible for the induction of MDR1 gene and resistance to chemotherapy in HIF1α-transfected human hepatoma cells as well as in human cervical cancer cells." (PMID 27705944, 2016). "Recently, it has been suggested that OPN may play a key role in maintaining stemness-like phenotypes in hepatocellular carcinoma (HCC) cell lines via αvβ3/NFκB/HIF1α signaling." (PMID 26068949, 2015). "Overexpression of HIF-1α is correlated with metastasis of hepatocellular carcinoma cells." (PMID 26474388, 2015). "In addition, normal liver cells have lower glycolytic activity than hepatoma cells, showing lower levels of glucose uptake, lactate production, and expressions/activities of glycolytic enzymes, as well as lower HIF1α level." (PMID 25855962, 2015). "Furthermore, HIF-1α inhibitor NSC restored the migratory capacity of infected hepatoma cells to parental levels and ablated Snail and Twist expression, confirming a HIF-1α dependent process." (PMID 22178269, 2012). "Furthermore, inhibiting HIF-1α significantly reduced HCV replication in hepatoma cell lines and primary hepatocytes, highlighting a dual role for this transcription factor in the viral life cycle and hepatoma migration." (PMID 22178269, 2012).
hepatocellular carcinoma (continued). "Inhibition of HIF-1α reversed the effect(s) of virus glycoproteins and infection on hepatoma migration and significantly reduced HCV replication, demonstrating a dual role for HIF-1α in deregulating cellular processes associated with tumor growth and in the viral life cycle." (PMID 22178269, 2012). "In the current study we hypothesized that ENMD-1198 could be used to inhibit HIF-1α activation in human hepatocellular cancer cells, which would reduce tumor growth and angiogenesis in vivo." (PMID 18651980, 2008). "In hepatocellular carcinoma (HCC), the combination of HIF-1α inhibitors with metabolic modulators such as palmitic acid and L-carnitine has shown potential in inducing apoptosis in hypoxic HCC cells by preventing lipid metabolism reprogramming." (PMID 40963621, 2025). "Furthermore, existing studies have only explored the role of USP39 in regulating tumor-related signaling pathways, including PI3K/AKT/HIF-1α and Wnt/β-catenin, across a limited range of cancers, such as hepatocellular carcinoma, endometrial cancer, and ovarian cancer." (PMID 40672756, 2025). "Under hypoxic conditions, the activation of hypoxia-inducible factor-1 alpha (HIF-1α) promotes EMT in hepatocellular carcinoma (HCC) and induces drug resistance by increasing P-glycoprotein (Multidrug Resistance 1; MDR1) expression." (PMID 41276852, 2025). "In hepatocellular carcinoma (HCC) cells, curcumin inhibits tumor invasion and metastasis by disrupting the HIF-1α-mediated epithelial–mesenchymal transition (EMT) process." (PMID 41515171, 2025). "Therefore, we believe that HIF-1a/PI3K may also have some mechanism in the development of hepatocellular carcinoma." (PMID 39050762, 2024). "In hepatocellular carcinoma (HCC), overexpression of PLIN2 promotes cell proliferation, potentially by inhibiting the degradation of HIF1α, which facilitates HCC cell proliferation." (PMID 39834787, 2024). "Furthermore, by reducing the expression of HIF-1α and HIF-2α, Tan IIA may also increase the susceptibility of hepatocellular carcinoma cells to the cytotoxic effects of Sorafenib." (PMID 37324455, 2023). "The activation of hypoxia-inducible factor (HIF)-1α under hypoxic conditions promotes EMT in hepatocellular carcinoma (HCC) and induces drug resistance by increasing the expression of MDR1." (PMID 37790807, 2023). "The present study verified that curcumin could inhibit the growth of hepatocellular carcinoma cells, and the main mechanisms are apoptosis induction, cell cycle arrest, and downregulation of the expression of cell signal transduction pathways HIF-1α/STAT3/VEGF." (PMID 37333486, 2023). "However, deficiency of Arid1a in mouse HCC (hepatocellular carcinoma) cells did not alter several of the angiogenesis-related genes, including Vegfa, Fgf2, Egfl7, Sdf1, Hif1a, Hif2a and Ang1." (PMID 38017409, 2023). "In hepatocellular carcinoma cells, LDHA is overexpressed due to downregulation of miR-383, triggering increased cell proliferation, invasion and glycolysis, MYC, NFκB, HIF-1α-mediated signaling enhances glycolysis in HCC by promoting upregulation of LDHA." (PMID 36686771, 2022). "In hepatocellular carcinoma (HCC) cells, the integration of glucose and cardiolipin anabolism, which is regulated by the mTORC1/HIF-1α/SREBP1 axis, promotes resistance to radiation by repressing cytochrome c extrusion." (PMID 36139006, 2022). "As an example, in hepatocellular carcinoma (HCC), HIF-1α augments lipid stabilization by alleviating FAO." (PMID 35205167, 2022). "Similar results are observed for miR-3662 which suppresses glycolysis by directly targeting Hypoxia-inducible factor 1-alpha (HIF-1α) in hepatocellular carcinoma (HCC)." (PMID 35348905, 2022). "Sustained anti-angiogenesis therapy increases the level of tumor hypoxia, leading to increased expression of HIF-1a, thereby contributing to the resistance to anti-angiogenesis therapy in hepatocellular carcinoma (HCC)." (PMID 35140333, 2022).